MIR645 (microRNA 645)
Synonyms: hsa-mir-645; MIRN645
Gene: MicroRNA gene on chromosome 20 (50,585,786 to 50,585,879, forward strand). Ensembl gene ENSG00000208018.
Homologues: Orthologues: chimpanzee ptr-mir-645 (100% identical).